KCNK12 (potassium two pore domain channel subfamily K member 12)
Description:
K(+) channel subunit that may homo- and heterodimerize to form functional channels with distinct regulatory and gating properties. Can heterodimerize with KCNK13 subunit to conduct K(+) outward rectifying currents at the plasma membrane. The homodimers are mainly retained in the endoplasmic reticulum compartment and may be targeted to the cell surface upon phosphorylation or other activation signals yet to be elucidated.
Synonyms: THIK-2; THIK2; K2p12.1
Tractability: Small molecule: it belongs to a druggable protein family. Antibody: UniProt places it where antibodies can reach, with high confidence; its Gene Ontology location is reachable by antibodies, with high confidence; UniProt predicts a signal peptide or a membrane-spanning region.
Gene: Protein-coding gene on chromosome 2 (47,509,290 to 47,570,985, reverse strand). Ensembl gene ENSG00000184261.
Subcellular location: Cell membrane; Endoplasmic reticulum membrane
Pathways (Reactome):
Muscle contraction: Phase 4 - resting membrane potential
Gene Ontology:
Molecular function: identical protein binding; potassium channel activity; protein binding; protein heterodimerization activity; potassium ion leak channel activity
Biological process: potassium ion transmembrane transport
Cellular component: endoplasmic reticulum membrane; plasma membrane; membrane
Genetic constraint (gnomAD): Loss-of-function variants: 6 observed, 12.9 expected, observed/expected ratio (o/e) 0.47, 90% interval 0.25 to 0.92. The synonymous counts are far from expectation, so gnomAD's model fits this gene poorly and the ratio says little. Missense variants: 360 observed, 391.53 expected, observed/expected ratio (o/e) 0.92, 90% interval 0.84 to 1. Synonymous variants: 266 observed, 191.55 expected, observed/expected ratio (o/e) 1.39, 90% interval 1.26 to 1.54.
Homologues: Orthologues: chimpanzee KCNK12 (100% identical), macaque KCNK12 (99% identical), pig KCNK12 (99% identical), mouse Kcnk12 (99% identical), rat Kcnk12 (99% identical), rabbit KCNK12 (98% identical), dog KCNK12 (98% identical), guinea pig KCNK12 (91% identical), tropical clawed frog kcnk12 (73% identical), zebrafish KCNK12 (68% identical), Caenorhabditis elegans twk-26 (20% identical), Caenorhabditis elegans twk-45 (20% identical), and 11 more. Paralogues in human: KCNK13 (61% identical), KCNK10 (21% identical), KCNK15 (20% identical), KCNK2 (20% identical), KCNK1 (19% identical), KCNK3 (19% identical), KCNK5 (19% identical), KCNK4 (18% identical), KCNK16 (18% identical), KCNK9 (18% identical), KCNK17 (17% identical), KCNK6 (17% identical), and 2 more.
Diseases named in the same sentence as KCNK12 in open-access papers:
KCNK12 is named in the same sentence as 13 diseases in open-access papers, as found by Europe PMC text mining. Sharing a sentence is not in itself a finding about the gene and the disease. The quoted sentences say what the papers report.
breast carcinoma (1 paper, 2025). "Breast cancer studies included E1 (KCNMB1), E4 (KCNN3), E9 (KCNH1, KCNK15), E15 (KCNT2), E22 (KCNK5, KCNK15), E33 (KCNQ1-OT1), E38 (KCNMA1), E48 (KCNJ9), and E63 (KCNK12)." (PMID 40867621, 2025).
lung carcinoma (1 paper, 2025). "Lung cancer studies included E3 (KCNK1), E8 (KCNK1, KCNN4), E12 (KCNH8, KCNMB2), E23 (KCNU1), E30 (KCNQ5-IT1), E35 (KCNK1), E43 (KCNK6), E49 (KCNN4), 2), E54 (KCNJ13), E63 (KCNK12), and E67 (KCNMB2)." (PMID 40867621, 2025).
Lynch syndrome (1 paper, 2021). An autosomal dominant hereditary neoplastic syndrome characterized by the development of colorectal carcinoma and a high risk of developing endometrial carcinoma, gastric carcinoma, ovarian carcinoma, renal pelvis carcinoma, and small intestinal carcinoma.
Tumor (2 papers, 2017 to 2021). "In each gene of the panel, Tumor QMSP was significantly higher than normal QMSP (CD1D: p < 0.001, KCNK12: p < 0.001, PAX5: p < 0.001)." (PMID 34530906, 2021).
KCNK12 also shares sentences with these, for which no sentence is quoted: acute lymphoblastic leukemia (1 paper); cancer (1); COVID-19 (1); malignant peripheral nerve sheath tumor (1); non-Hodgkin lymphoma (1); papillary thyroid carcinoma (1); synovial sarcoma (1); thyroid cancer (1); tubular breast carcinoma (1).